HULC (hepatocellular carcinoma up-regulated long non-coding RNA)
Diseases named in the same sentence as HULC in open-access papers (continued):
Sharing a sentence is not in itself a finding about the gene and the disease.
cancer (57 papers, 2015 to 2025). A tumor composed of atypical neoplastic, often pleomorphic cells that invade other tissues. "Other lncRNAs including AC006160.1, Loc100506691, lncRNA-AF085935, and HULC are also associated with cancers and metformin." (PMID 36849958, 2023). "Among the input set of 15 cancer‐related lncRNAs, 28 and nine co‐expressed protein‐coding genes were identified to be associated with HULC and ZNF667‐AS1, respectively." (PMID 32869528, 2020). "In summary, while the association of lncRNA HULC with cancer is well-established, the precise mechanistic contribution of the rs7763881 SNP to HULC function remains to be determined." (PMID 33329688, 2020). "In conclusion, HULC rs7763881 A/C polymorphism was associated with decreased overall risk of cancer." (PMID 29802154, 2018). "In this review, we examine current evidence regarding the deregulation of HULC in human cancers and its associated mechanisms." (PMID 27781386, 2017). "Although the mechanisms underlying HULC overexpression in many cancer types remain uncertain, emerging evidence have hinted at complex interplay between environmental and host factors in the regulation of HULC expression." (PMID 27781386, 2017). "Analysis of 216 patients from three eligible studies demonstrated association between HULC expression levels and the number of cancer patients with DM." (PMID 28199963, 2017). "The expression of HULC was significantly associated with OS of cancers (HR = 2.12; 95% CI 1.61 – 2.79; P<0.00001)." (PMID 29137338, 2017). "In conclusion, this meta-analysis suggested that high expression of HULC was significantly associated with OS of cancer." (PMID 29137338, 2017). "In addition, our study was the first meta-analysis to show the significant association between the lncRNA ANRIL, MALAT1, HOTTIP, and HULC polymorphisms and cancer risk." (PMID 29802154, 2018). "Therefore, our data demonstrated that HULC was an independent OS factor among cancer patients and its high expression was associated with shorter OS." (PMID 28199963, 2017). "According to meta-analysis result, it can be seen that the expression of HULC might be associated with poor overall survival in various types of carcinomas." (PMID 29145271, 2017). "Additional research examining the presence of lncRNAs in the peripheral blood of cancer patients indicates that the concentration of HULC, a distinct lncRNA, is elevated by 10 to 30 times in the blood of cancer patients compared to that of healthy donors." (PMID 39200161, 2024). "Initially identified as a highly upregulated transcript in the blood/cancer tissue of HCC patients, HULC is a 482 lncRNA encoded by a gene located on locus 6p24.3." (PMID 39596302, 2024). "Examples of this are HOXD-AS1 and ZFAS1 function in invasion and metastasis, HULC in cell metabolism and proliferative signaling or H19 in both the maintenance of cancer stem cells and angiogenesis." (PMID 34071216, 2021). "Another paradigm of this function is HULC, a very abundant lncRNA in hepatocellular carcinoma, and many other cancer types, that resembles the mammalian LTR transposon 1A." (PMID 33142861, 2020). "Although HULC has been found to be crucial for several cancer types, this is the first report on HULC in human OSCC." (PMID 30677230, 2019). "HULC is known to promote multiple types of cancer and to be overexpressed in HCC, with such overexpression being an independent unfavorable factor for overall survival and disease-free survival time in HCC patients." (PMID 31645479, 2019). "HULC functions as an oncogene in human cancer which promotes tumorigenesis by regulating multiple signaling pathways." (PMID 31886187, 2019). "The expression levels of numerous lncRNAs are altered in several types of cancer, and several lncRNAs are already used as molecular tools for diagnosis and prognosis of cancer like H19, HULC and HOTAIR." (PMID 29755696, 2018).
cancer (continued). "For example, two published meta-analyses individually analyzed the possibility of lncRNA HULC or UCA1 as a potential prognostic biomarker in the human cancer." (PMID 29568404, 2018). "A number of groups addressed HULC dysregulation and its molecular mechanisms in various cancer cells proliferation, migration, apoptosis, and metastasis but limited reports have focused on autophagy." (PMID 30693021, 2018). "Since HULC expression has been shown during cancer growth and metastasis, it is a promising prognostic biomarker candidate for human cancers." (PMID 28199963, 2017). "Since the role of HULC as a molecular biomarker in human cancer was unclear, our study explored the prognostic value of HULC in cancer patients using the meta-analysis." (PMID 28199963, 2017). "Our data showed that higher HULC expression was indicative of advanced cancer and highlighted poor prognosis." (PMID 28199963, 2017). "A variety of lncRNAs, including ANRIL, MEG3 and HULC, either promote or suppress the development of cancer." (PMID 26448942, 2015). "Sp transcription factors play a role in the proliferation, survival, migration/invasion of several cancer cell lines and we used RNAi to investigate the differential effects of Sp1, Sp3, Sp4 and HULC knockdown on HCC cell proliferation and survival." (PMID 26317792, 2015). "Results of this study demonstrate the importance of HULC and Sp transcription factors in HCC, suggesting that both HULC and Sp1 can be targeted by anticancer agents that are known to downregulate Sp transcription factors in other cancer cell lines and tumors." (PMID 26317792, 2015). "Since then, the function of HULC has been demonstrated in multiple cancer types." (PMID 36213832, 2022). "This suggested that HULC interacts in vivo with signaling pathways that promote cancer formation." (PMID 36213832, 2022). "HULC is deregulated in cancer and acts as the potential biomarker and therapeutic target." (PMID 33425489, 2021). "HULC is a lncRNA that promotes cancer cell EMT, invasion, and metastasis." (PMID 34439315, 2021). "The expression levels of HULC in cancer patients have been correlated with their clinical outcome." (PMID 33142861, 2020). "Besides ANRIL, CCAT2, PCAT1, HULC, and CUPID1/2, there are numerous other cancer-associated lncRNAs listed in the relevant databases, several of which contain disease-associated SNPs." (PMID 33329688, 2020). "A recent study has indicated that lncRNA interactions with miRNA and mRNA—such as H19, MALAT1, and KCNQ1OT1, HULC, and HOTAIR—could be potential diagnostic and prognostic biomarkers in cancer." (PMID 31164794, 2019). "Therefore, further well-designed and high-quality studies are needed to confirm the function of HULC in various cancers." (PMID 28199963, 2017). "In conclusion, the current meta-analysis demonstrated that TUG1, SPRY4-IT1, and HULC might serve as a moderate predictor of survival in human cancer." (PMID 29145271, 2017). "In conclusion, this meta-analysis suggested that HULC was a biomarker of the prognosis of cancer." (PMID 29137338, 2017). "Additionally, our results propose rs7763881 SNP as a new mechanism regulating HULC expression in cancer." (PMID 29176650, 2017). "Studies of HULC in HCV-related carcinoma are scarce; however, the discordance of our results (in two independent studies and with different technical approaches) may indicate that HULC deregulation in HCV-HCC may occur through pathways other than HBV-HCC, prompting further investigation." (PMID 40699747, 2025). "HULC could promote cancer cell survival, proliferation, and invasion." (PMID 36213832, 2022). "Therefore, the lncRNA-TUG1, SPRY4-IT1, and HULC may function as potential markers in predicting the prognosis of patients with various kinds of cancer." (PMID 29145271, 2017).
cancer (continued). "Thirty-one proteins remain after screening (protein name marked in red), in which YBX1 has been reported to interact with several oncogenic lncRNAs, including TP53TG1, HULC, HOXC-AS3, and lincNMR, thereby regulating cancer progression and oncogene expression." (PMID 34266873, 2021). "Among the 15 cancer‐related lncRNAs, ZNF667‐AS1, HULC, LINC01198, and NFIA‐AS1 have been reported in previous studies." (PMID 32869528, 2020). "Therefore, lncRNA HULC may be a therapeutic target for cancer therapy." (PMID 32010942, 2020). "Previous studies have reported that CREB stimulates the expressions of several cancer promoters like YAP, HULC, c-FLIP(L), and MKP-1." (PMID 30881868, 2019). "For example, the lncRNAs TUG1, UCA1, SPRY4-IT1, HULC, HOTTIP, H19 and HOTAIR were found to be novel promising biomarkers for poor prognosis in human cancers." (PMID 29308050, 2018). "First, we validated 3 well-known lncRNAs (H19, HULC, and PVT1), which have been reported to be involved in a variety of cancers." (PMID 30305026, 2018). "Several lncRNAs, such as HULC, HOTAIR, HOTTIP, GAS5, and HOST2, have been identified as miRNA targets in various cancers, and these findings provide further understanding of lncRNA regulation during tumorigenesis." (PMID 28492554, 2017). "Therefore, a systematic review and meta-analysis has been carried out to explore the expression of these 3 well-known lncRNAs (TUG1, SPRY4-IT1, and HULC) and lymph node metastasis and the overall survival to prove these 3 lncRNAS might serve as biomarkers in cancer prognosis and diagnosis." (PMID 29145271, 2017). "To investigate the role of ESM-1 in the regulation of cancer malignancy by HULC, we transfected the ESM-1 expression plasmid into HULC-silenced U87MG and U251 cells to observe the reversed effect of HULC silencing in a subsequent experiment." (PMID 26894862, 2016). "In HCC, however, to date, only a few studies implicated lncRNAs, such as MALAT1, HOTAIR, HOTTIP/HOXA13, H19, HULC, MEG3, in the cancer pathogenesis." (PMID 25686840, 2015). "In addition, metformin action on other types of cancers by regulating ten lncRNAs including AC006160.1, Loc100506691, lncRNA-AF085935, SNHG7, HULC, UCA1, H19, MALAT1, AFAP1-AS1, AC026904.1 is described." (PMID 36849958, 2023). "Unexpectedly, the high expression of HULC was negatively correlated with OS time in CHOL, while HULC expression was not significantly correlated with OS time in other cancers." (PMID 35183058, 2022). "A large number of articles have identified that lncRNAs such as lncRNA PVT1, lncRNA HULC, and lncRNA CRNDE are closely related to the initiation and progression of various cancers and could serve as prognostic biomarkers." (PMID 32493915, 2020). "We also measured HULC levels in four OSCC cell lines (SCC15, SCC25, SCC9 and CAL27), which revealed that HULC expression was markedly up‐regulated in the cancer cell lines relative to that in a normal oral keratinocyte cell line (human oral keratinocyte (HOK) cells)." (PMID 30677230, 2019). "Some autophagy-modulated lncRNAs described in this review are very specific with identical tissue types, for example HULC, PCA3, PVT1 may serve as a potential biomarkers and target therapy in identical cancer types." (PMID 30693021, 2018). "The lncRNAs have been proved to engage in cancer metastasis such as HOTAIR, MALAT1 and HULC." (PMID 28969031, 2017). "Consistent with this hypothesis, several lncRNAs, such asPTENP1, HULC, GAS5, loc285194,HOTAIR as well as HOTTIP, have been identified as miRNA targets in various cancers, which provide further layers of understanding lncRNA regulation during carcinogenesis." (PMID 26710269, 2015). "Thus, HULC, LINC02535, LINC00261, and KCNQ1OT1 may act as competing endogenous RNAs (ceRNAs) in various cancers, including HCC." (PMID 40699747, 2025).
cancer (continued). "For instance, the lncRNA HULC, which is specifically overexpressed in HCC, could activate autophagy, thereby promoting HCC development, while concomitantly reducing chemosensitivity of cancer cells." (PMID 35159028, 2022). "HULC expression was higher in the cancer tissues than in the normal tissues, and, similarly, was higher in OSCC cell lines than in normal keratinocytes, and HULC down‐regulation in the OSCC cell lines SCC15 and SCC25 affected the proliferation, migration and invasion abilities of these cells." (PMID 30677230, 2019). "The high expression of HULC was negatively correlated with OS time in CHOL, while HULC expression was not significantly correlated with OS time in other cancers." (PMID 35183058, 2022).
digestive system tumors (2 papers, 2022 to 2025). "The up-regulated expression level of HULC was associated with poorer overall survival (OS) in patients with digestive system tumors (HR = 1.83, 95% CI: 1.05-3.19, P = 0.033)." (PMID 35183058, 2022). "The current body of evidence highlights the pivotal role of HULC in the initiation, progression, and metastasis of digestive system tumors, underscoring its promise as a target for future precision medicine strategies." (PMID 40909946, 2025). "The results suggested that the increased expression of HULC was significantly related to the poor differentiation of the digestive system tumors (OR = 1.38, 95% CI: 1.02-1.87, P = 0.035)." (PMID 35183058, 2022). "The pooled results suggested that high expression level of HULC had a significant correlation with poor survival prognosis in patients with digestive system tumors." (PMID 35183058, 2022). "Furthermore, HULC has been studied most extensively within the context of digestive system cancers.Therefore, we have decided to focus on digestive system tumors to thoroughly investigate the biological functions and clinical significance of HULC in this area." (PMID 40909946, 2025). "The up-regulated of HULC could be used as a novel predictor of poor prognosis in patients with digestive system tumors." (PMID 35183058, 2022). "Therefore, we believe that high expression of lncRNA HULC in patients with digestive system tumors tend to have a poor prognosis." (PMID 35183058, 2022). "Therefore, as a promising therapeutic target, HULC has the following advantages: 1) High tissue specificity: HULC is significantly upregulated in digestive system tumors and is expressed at a lower level in most normal tissues, minimizing potential off-target effects." (PMID 40909946, 2025). "Also, some studies have shown that HULC expression is dysregulated in digestive system tumors." (PMID 35183058, 2022).
digestive system cancer (1 paper, 2025). A primary or metastatic malignant neoplasm involving any part of the digestive system. "In this review, we summarize the expression patterns, biological functions, and molecular mechanisms of HULC in digestive system cancers, and discuss its potential as a novel diagnostic biomarker and therapeutic target." (PMID 40909946, 2025). "This review comprehensively summarizes recent advances in understanding the biological roles, molecular mechanisms, and clinical implications of HULC in digestive system cancers." (PMID 40909946, 2025). "Multiple studies have shown that HULC is significantly upregulated in various digestive system cancers." (PMID 40909946, 2025). "Future investigations should leverage cutting-edge sequencing platforms and innovative functional assays to elucidate the oncogenic role and clinical significance of HULC in digestive system cancers." (PMID 40909946, 2025).
HULC also shares sentences with these, for which no sentence is quoted: lung carcinoma (4 papers); bladder cancer (3); ovarian carcinoma (3); atherosclerosis (1); Cholestatic liver disease (1); diabetic cardiomyopathy (1); esophageal squamous cell carcinoma (1); fibrosis (1); gastric polyps (1); Insulin resistance (1); lung squamous cell carcinoma (1); lymph node metastasis (1); metastasis (1); multiple sclerosis (1); neuroblastoma (1); non-small cell lung carcinoma (1); nonalcoholic fatty liver disease (1); oesophageal cancer (1); oral cavity cancer (1); Oral squamous cell carcinoma (1); polyp (1); severe combined immunodeficiency (1); stomach cancer (1); triple-negative breast carcinoma (1); type 2 diabetes (1).